NLRP3 (NLR family pyrin domain containing 3)
Diseases named in the same sentence as NLRP3 in open-access papers (continued):
Sharing a sentence is not in itself a finding about the gene and the disease.
rhabdomyolysis (5 papers, 2015 to 2024). Necrosis or disintegration of skeletal muscle often followed by myoglobinuria. "Recently, we highlighted a potential role for urate crystals in generating oxidative stress and activating the NLRP3 inflammasome in an animal model of rhabdomyolysis-associated AKI." (PMID 31018590, 2019). "Inflammation is the main pathogenic feature of AKI induced by rhabdomyolysis, and previous studies have shown that pattern recognition receptors such as TLR4 and NLRP3 are upregulated in the kidney in RIAKI." (PMID 33202867, 2020). "Inhibition of the NLRP3 inflammasome may also be beneficial in other diseases, such as sickle anemia, β‐thalassemia, plasmodium infection, and rhabdomyolysis, which produce many hemes." (PMID 33783986, 2021). "Therefore, we investigated the role of NLRP3 inflammasomes in the pathogenesis of RIAKI using a glycerol-induced murine rhabdomyolysis model." (PMID 26045078, 2015). "NLRP3 depletion decreased the mRNA expression of inflammatory cytokines, including TNF-α, IL-1β, and IL-6, induced by rhabdomyolysis." (PMID 33202867, 2020). "Finally, as the pathogenesis of rhabdomyolysis is multifactorial, the role of other concomitant factors, acting either as priming stimuli or directly activating the NLRP3 inflammasome, should not be ignored." (PMID 31018590, 2019).
Right ventricular hypertrophy (5 papers, 2022 to 2026). In this case the right ventricle is more muscular than normal, causing a characteristic boot-shaped (coeur-en-sabot) appearance as seen on anterior- posterior chest x-rays. "Our data indicate that dapagliflozin attenuates right ventricular systolic pressure, right ventricular hypertrophy, and pulmonary vascular remodeling and decreases NLRP3 inflammasome activation in MCT-induced PAH rats." (PMID 35413880, 2022). "Pharmacological inhibition of complement C3 cleavage (CP40-KK) could ameliorate MCT-induced NLRP3 inflammasome activity, pulmonary vascular remodeling, and right ventricular hypertrophy." (PMID 38365806, 2024).
sarcoidosis (5 papers, 2021 to 2025). Sarcoidosis is a multisystemic disorder of unknown cause characterized by the formation of immune granulomas in involved organs. "The activation of the NLRP3 inflammasome pathway was present in 85% of patients with sarcoidosis at diagnosis, and its presence is associated with a worse clinical outcome of the disease." (PMID 37628972, 2023). "Furthermore, the presence of NLRP3 activation at diagnosis was associated with a chronic disease course of sarcoidosis." (PMID 37628972, 2023). "Furthermore, the NLRP3 pathway seems most active in patients with sarcoidosis at diagnosis, and its presence is associated with worse clinical outcomes of the disease." (PMID 37628972, 2023). "It is shown that significant upregulation of the NLRP3 pathway in sarcoid patients in both bronchoalveolar lavage (BAL) cells and miR-223 knockout and NLRP3 knockout mice." (PMID 39904950, 2025). "Over the years, multiple studies have already described a possible role for the mTORC1, JAK/STAT, and NLRP3 inflammasome inflammatory pathways in the pathogenesis of sarcoidosis." (PMID 37628972, 2023). "When comparing the presence of the three studied pathways, we found that compared to mTORC1 and STAT, the activation of the NLRP3 inflammasome pathway had both the highest prevalence (85%) and IHC score (4.27 ± 2.60) in patients with sarcoidosis at diagnosis." (PMID 37628972, 2023). "It is reported that downregulated mRNA levels of miR-223, a direct downregulator of the NLRP3 inflammasome, induce the increased expression of IL-1β in AMs from sarcoidosis patients than in healthy volunteers." (PMID 35819638, 2022). "Increased expression of IL-1β by BAL MNPs indicates an upregulation of the inflammatory NLRP3 pathway as previously shown to be activated in sarcoidosis." (PMID 33446605, 2021). "Besides mTOR, JAK/STAT and Rac1 pathway, NLRP3 pathway is another important pathway activated in granuloma formation of sarcoidosis." (PMID 39904950, 2025). "Our finding of different new conceptual inflammatory tissue phenotypes in sarcoidosis could possibly guide future treatment studies using the available inhibitors of either NLRP3, JAK-STAT, and mTORC1 inhibitors in a more personalized medicine approach." (PMID 37628972, 2023). "The NLRP3 signaling pathway was active in the majority of sarcoidosis patients (85.0%)." (PMID 37628972, 2023). "Our finding of different new conceptual inflammatory tissue phenotypes in sarcoidosis could possibly guide future treatment studies using the available inhibitors of either NLRP3, JAK-STAT, and mTORC1 in a more personalized medicine approach." (PMID 37628972, 2023). "As with the other two key pathways, the NLRP3 inflammasome could also be a potential target for treatment in sarcoidosis." (PMID 37628972, 2023). "It is suggested that SAA may activate the NLRP3 inflammasome as a DAMP to participate in the pathogenesis of sarcoidosis." (PMID 35819638, 2022). "As a future direction, we plan to investigate interactions between HIF and other signaling pathways identified in the pathogenesis of sarcoidosis as mTOR, NLRP3 inflammasome, JAK/STAT, or heat shock proteins, already known to interfere with the HIF/hypoxia pathway." (PMID 34456926, 2021). "Therefore, measuring the activity of the NLRP3 inflammasome signaling pathway in tissue might serve as a predictive biomarker for a more chronic disease course in patients with sarcoidosis." (PMID 37628972, 2023). "Collectively, the NLRP3 inflammasome may play a critical role in sarcoidosis." (PMID 35819638, 2022). "The observation that patients with active NLRP3 more often received a third-line treatment for sarcoidosis compared to patients without the activation of this pathway at diagnosis strengthens this association." (PMID 37628972, 2023). "Additionally, whether pyroptosis participates in CF and sarcoidosis or not is largely unknown, though the activation of NLRP3 inflammasome is found in CF and sarcoidosis." (PMID 35819638, 2022).
sarcoidosis (continued). "In our study, we found that NLRP3, JAK-STAT, and mTORC1 are not simultaneously active in all patients’ sarcoidosis at diagnosis." (PMID 37628972, 2023). "The inflammatory pathways NLRP3, JAK-STAT, and mTORC1 are not simultaneously active in all patients’ sarcoidosis at diagnosis." (PMID 37628972, 2023).
Streptococcus pneumonia (5 papers, 2019 to 2021). "In summary, the QFY anti-streptococcus pneumonia effect appears to be associated with activation of autophagy through down-regulation of upstream autophagy pathway events involving NLRP3/mTOR." (PMID 35111047, 2021). "We previously demonstrated that maturation and secretion of IL-1β require activation of AIM2 and NLRP3 inflammasome in Streptococcus pneumonia-infected macrophages and neutrophils." (PMID 34017331, 2021). "Although the biology of NLRP3 has been widely studied in macrophages and dendritic cells, studies have shown that neutrophils are the main source of the NLRP3-dependent IL-1β production in Staphylococcus aureus and Streptococcus pneumoniae mouse infections." (PMID 33440601, 2021). "Mice lacking NLRP3 were more susceptible than wild-type mice to infection with M. kansasii, group B Streptococcus, C. rodentium, Burkholderia pseudomallei, and Streptococcus pneumonia." (PMID 31417575, 2019).
systemic inflammatory response syndrome (5 papers, 2022 to 2025). SIRS is a serious condition related to systemic inflammation, organ dysfunction, and organ failure. "The NLR Family Pyrin Domain-Containing 3 (NLRP3) inflammasome/caspase-1/IL-1β pathway may be involved to some extent in the occurrence of systemic inflammatory response syndrome (SIRS)." (PMID 40041174, 2025). "Interestingly, IL-1β, a final product of NLRP3 inflammasome activation, is observed to play a significant role in NET formation and induces NETosis in systemic inflammatory response syndrome (SIRS) and abdominal aortic aneurysms (AAA)." (PMID 36851139, 2023).
toxoplasmosis (5 papers, 2017 to 2025). A parasitic disease contracted by the ingestion or fetal transmission of toxoplasma gondii. "In toxoplasmosis, NLRP3 is crucial for regulating the Toxoplasma gondii burden, controlling parasite growth and proliferation, and managing parasite-induced cell death." (PMID 40586570, 2025). "Our results are consistent with those of previous studies, that is, T. gondii triggers NLRP3 or NLRP1, which leads to parasite restriction and resistance to toxoplasmosis, and p38 MAPK is important for the regulation of NLRP1 or NLRP3 inflammasome activation and IL-1β secretion." (PMID 33712075, 2021). "Because NLRP3-dependent production of IL-1β and nitric oxide (NO) in Toxoplasma-infected human cells is involved in the GRA15-dependent virulence mechanism, blocking NO or IL-1β production in the host could represent a novel therapeutic approach for treating human toxoplasmosis." (PMID 30301855, 2018).
tularemia (5 papers, 2009 to 2023). Tularemia is an infection caused by the bacterium Francisella tularensis. "It has been reported that Nlrp3 exacerbates the symptoms of pulmonary tularemia primarily by causing excessive infiltration of immature neutrophils in the lungs of mice infected with F. tularensis, indicating a pathogenic role for Nlrp3." (PMID 34690967, 2021). "Collectively, this study advances our understanding of the detrimental role of Nlrp3 in tularemia pathogenesis." (PMID 34690967, 2021). "Here, we report that Nlrp3-/- mice exhibit resistance to Ft infection through mature myeloid cell response in lungs and decreased myeloid and lung cell death during pulmonary tularemia." (PMID 27926940, 2016). "This study advances our understanding of the detrimental role of Nlrp3 and demonstrates that Nlrp3 could be a potential target for the development of effective therapeutics for the treatment of tularemia." (PMID 34690967, 2021). "Our results also suggest that the diminished levels of IL-1β and IL-18 in the lungs of Nlrp3-/- mice may be sufficient to support their critical protective function during pulmonary tularemia." (PMID 27926940, 2016). "As the deficiency of Nlrp3 limits neutrophil cell death early during infection and lung epithelial cell death later in infection, Nlrp3-dependent necroptosis might help explain the pathology and host mortality accompanying pulmonary tularemia." (PMID 27926940, 2016). "Alternatively, Nlrp3 might play an inflammasome-independent role in the pathogenesis of pulmonary tularemia in wildtype mice." (PMID 27926940, 2016). "As IL-1β/IL-18 levels are reduced in Ft LVS infected Nlrp3-/- mice, the amounts of these cytokines required for protection during pulmonary tularemia may be much lower than previously thought." (PMID 27926940, 2016). "Collectively, these data suggest that Nlrp3-dependent, but Asc, caspase-1/11, and caspase-3-independent cell death, which is likely necrosis/necroptotic, contributes to death of lung myeloid and epithelial cells during pulmonary tularemia." (PMID 27926940, 2016). "In contrast to the anticipated minimal, or perhaps absent, role of Nlrp3 in the pathogenesis of pulmonary tularemia, we find that Nlrp3 is a host susceptibility factor." (PMID 27926940, 2016). "Furthermore, Nlrp3-deficient mice exhibit reduced lung pathology, possibly due to NLRP3-induced cell death contributing to the negative pathology during tularemia." (PMID 35626718, 2022). "The results from this study ruled out that the inflammasome-mediated function of Nlrp3 is not responsible for its detrimental role in tularemia pathogenesis." (PMID 34690967, 2021). "However, the activation of Aim2 and Nlrp3-inflammasomes are repressed in macrophages infected with F. tularensis LVS, and both are dispensable for vaccine-induced immunity against pulmonary tularemia." (PMID 34690967, 2021). "Intriguingly, severe necrosis during pulmonary tularemia requires Nlrp3, but appears largely independent of caspase-1 and Asc in both myeloid and lung epithelial cells." (PMID 27926940, 2016). "Given the requirement for the mature neutrophils early in infection and the late appearance of elevated IFNγ, it is unlikely that resistance to Ft in the absence of Nlrp3 results from transcriptional alterations in lung Th1/Th2 cytokines during pulmonary tularemia." (PMID 27926940, 2016).
ventricular dilatation (5 papers, 2022 to 2024). "According to T2-weighted images, WT rats had more severe ventricular dilatation than Nlrp3−/− rats after ICH-IVH." (PMID 36869068, 2023). "Pharmacological inhibition of NLRP3 could prevent right ventricular dilation and dysfunction of mice with ARVC." (PMID 38185631, 2024). "P2X7 inhibition (using silencing RNA) could prevent the formation of the NLRP3 inflammasome, limit infarct size and cardiac enlargement in AMI, and alleviate VR on the 7th day, which was characterized by slight ventricular dilatation and dysfunction." (PMID 35615687, 2022).
X-linked adrenoleukodystrophy (5 papers, 2016 to 2020). X-linked adrenoleukodystrophy (X-ALD) is a peroxisomal disorder resulting in cerebral demyelination, axonal dysfunction in the spinal cord leading to spastic paraplegia, adrenal insufficiency and in some cases testicular insufficiency. "Additionally, the NLRP3 gene is known to be associated with many non-infectious diseases of the nervous system, such as spinal cord injury and X-linked adrenoleukodystrophy." (PMID 32116990, 2019). "And subsequent study found that 25-HC promoted robust NLRP3 inflammasome assembly and activation via potassium efflux, mitochondrial reactive oxygen species (ROS), and LXR-mediated pathways in X-linked adrenoleukodystrophy (X-ALD)." (PMID 33274010, 2020).
acute GVHD (4 papers, 2014 to 2023). "Furthermore, activation of the NLRP3-inflammasome during early conditioning in mice contributes to the development of acute GVHD." (PMID 25101080, 2014). "Data on inflammasomes in allo-HSCT are not yet abundant, but NLRP3 and possibly other inflammasomes that sense endogenous danger signals such as ATP and uric acid and induce IL-1β release seems to have a role in the pathogenesis of acute GVHD." (PMID 25101080, 2014).
acute tubular necrosis (4 papers, 2016 to 2024). "Folic acid (FA)-induced acute tubular necrosis (ATN) is tightly associated with NLRP3 inflammasome activation." (PMID 33247121, 2020). "Folic acid-induced acute tubular necrosis (ATN) is another mouse model of NLRP3-dependent inflammation." (PMID 39179640, 2024).
allergic contact dermatitis (4 papers, 2018 to 2022). An inflammatory skin condition caused by an immune response to direct contact between the skin and an allergen. "Our recent study revealed that the NLRP3 inflammasome was involved in hexavalent chromium-induced allergic contact dermatitis." (PMID 34983566, 2022). "We previously revealed the similar result that PT attenuates allergic contact dermatitis via inhibition of IL-1β-related NLRP3 inflammasome activation." (PMID 34983566, 2022). "Researchers have confirmed that the NLRP3 inflammasome activation is involved in contact hypersensitivity and inhibition of NLRP3 inflammasome signaling presents a potential strategy for prevention of allergic contact dermatitis." (PMID 33634989, 2021). "Among all PRRs, several studies emphasize the role of NOD-, LRR- and pyrin domain-containing protein 3 (NLRP3) inflammasome on the allergic contact dermatitis (ACD) sensitization phase." (PMID 32933004, 2020). "Our results were similar to a recent study that investigated the capacity of allergic contact dermatitis-relevant Cr(VI) compounds to trigger cellular innate immune activation and showed that Cr(VI) is a potent NLRP3 inflammasome activator." (PMID 30486377, 2018).
cataract (4 papers, 2016 to 2024). Partial or complete opacity of the crystalline lens of one or both eyes that decreases visual acuity and eventually results in blindness. "Overall, these findings highlight that blocking the NLRP3 inflammasome in LECs can counteract UA-induced cataract progression by reducing key signaling mediators and senescent biomarkers." (PMID 38461179, 2024). "H2O2-induced oxidative stress could activate NF-κB signaling and increase NLRP3 expression significantly in human lens epithelial cells via caspase-1 activation and maturation of IL-1β, which contributes to pyroptosis and the development of cataracts." (PMID 34925047, 2021). "Several studies have demonstrated that pyroptosis might have a role in cataract formation and that the levels of pyroptosis markers, such as NLRP3, pro-caspase-1, active caspase-1, GSDMD-N, IL-1β, and IL-18, are significantly increased in the capsule tissues or cells of cataract patients." (PMID 34925047, 2021).
chronic myelomonocytic leukemia (4 papers, 2020 to 2024). A myelodysplastic/myeloproliferative neoplasm which is characterized by persistent monocytosis, absence of a Philadelphia chromosome and BCR/ABL fusion gene, fewer than 20 percent blasts in the bone marrow and blood, myelodysplasia, and absence of PDGFRA or PDGFRB rearrangement. "Regarding increased pro-inflammatory signaling, one publication reported the oncogenic KRASG12D mutation as a driver for elevated myeloproliferation and chronic myelomonocytic leukemia (CMML) through activation of the NLRP3 inflammasome and caspase-1-mediated cleavage of pro-inflammatory cytokines." (PMID 32604862, 2020). "Additionally, the NLRP3 inflammasome has been linked to the development of myeloid leukemias, such as chronic myelomonocytic leukemia (CMML), juvenile myelomonocytic leukemia (JMML), and AML, particularly in the context of KRAS mutations." (PMID 39769450, 2024). "This important role of the NLRP3 inflammasome in the pathogenesis of myeloid malignancies and the newly identified KRAS/RAC1/ROS/NLRP3/IL-1β axis has been demonstrated in chronic myelomonocytic leukemia (CMML), juvenile myelomonocytic leukemia (JNNL) and AML patients harboring the KRAS mutation." (PMID 33525345, 2021).
chronic otitis media (4 papers, 2021 to 2025). Chronic form of otitis media (disease). "In our study, NLRP3-deficient mice exhibited reduced inflammation in chronic otitis media models, suggesting that NLRP3 could be a potential therapeutic target for sensorineural hearing loss." (PMID 40114926, 2025). "Furthermore, the levels of NLRP3, ASC, and caspase-1 mRNA were significantly upregulated in middle ear tissue samples from patients with cholesteatoma or chronic otitis media." (PMID 34805037, 2021).
complication (4 papers, 2018 to 2024). Any disease or disorder that occurs during the course of, or because of, another disease, treatment, or procedure. "NLRP3 inflammasome has been implicated in various diabetic cardiovascular complications, and its activation has recently been indicated as a possible marker of cardiovascular risk." (PMID 38774996, 2024).